ORAI1 (ORAI calcium release-activated calcium modulator 1)
Diseases named in the same sentence as ORAI1 in open-access papers (continued):
Sharing a sentence is not in itself a finding about the gene and the disease.
tubular aggregate myopathy (19 papers, 2016 to 2026). "Any modifications in the SOCE process resulting in disease and mutations in STIM1 and ORAI1 have been linked to tubular aggregate myopathy in humans." (PMID 40841884, 2025). "Tubular aggregate myopathy (TAM) is caused by mutations in ORAI1 and STIM1 subunits of the Ca2+-release-activated Ca2+ (CRAC) channel." (PMID 39420094, 2024). "The human mutation in the Orai1 calcium channel responsible for tubular aggregate myopathy is transferred to create a mouse model that offers insight into the underlying pathological etiology." (PMID 39420094, 2024). "The pathogenic Orai1 L138F mutation located in TM2 was identified using whole exome sequencing in a Japanese family with tubular aggregate myopathy (TAM) and was found to mediate STIM1-independent Ca2+ entry." (PMID 36806330, 2023). "Here, we examined a poorly understood gain-of-function (GOF) human Orai1 disease mutation, L138F, that causes tubular aggregate myopathy." (PMID 36806330, 2023). "A previous report showed that human mutation Orai1 L138F causes tubular aggregate myopathy with hypocalcemia in human patients." (PMID 36806330, 2023). "In contrast, dominant STIM1 and ORAI1 gain-of-function (GoF) mutations inducing excessive Ca2+ entry through SOCE over-activation were found in patients with tubular aggregate myopathy (TAM) and Stormorken syndrome (STRMK)." (PMID 33250786, 2020). "Gain‐of‐function mutations in STIM1 or ORAI1 isoforms cause tubular aggregate myopathy (TAM), a skeletal muscle disorder with muscular pain, weakness and cramping." (PMID 30382595, 2019). "Recently, mutations in genes encoding two major proteins in SOCE, stromal interaction molecule 1 (STIM1) and calcium release-activated calcium channel protein 1 (ORAI1), have been identified as a cause of tubular aggregate myopathy (TAM)." (PMID 27879676, 2016). "In contrast, dominant STIM1 and ORAI1 gain-of-function mutations give rise to tubular aggregate myopathy and Stormorken syndrome (TAM/STRMK), forming a clinical spectrum encompassing muscle weakness, thrombocytopenia, ichthyosis, hyposplenism, short stature, and miosis." (PMID 33250786, 2020). "Gain-of -function mutations in STIM1 and Orai1 are increasingly recognized as a genetic syndrome that includes hyposplenism, platelet bleeding diathesis, and tubular aggregate myopathy (TAM1)." (PMID 38300705, 2024). "Inhibition of the Ca2+ channel ORAI1 rescues the multi-systemic signs in a mouse model for tubular aggregate myopathy and Stormorken syndrome." (PMID 38516893, 2024). "On the other hand, dominant gain-of-function (GoF) mutations in the STIM1 and ORAI1 proteins lead to enhanced SOCE function and constitutive Ca2+ entry in the absence of ER/SR store depletion that results in tubular aggregate myopathy (TAM)." (PMID 39420094, 2024).
Stormorken syndrome (18 papers, 2019 to 2025). Stormorken-Sjaastad-Langslet syndrome is characterized by thrombocytopathy, asplenia, miosis, muscle fatigue, migraine, dyslexia, and ichthyosis. "Overall, these data demonstrate that loss of helical instability in TMD4, which activates Orai1 and causes Stormorken syndrome, also blocks recognition by rhomboid and thus has a negative impact on its ability to perform conformational surveillance." (PMID 34800360, 2021). "Furthermore, our work reveals that RHBDL2 has strongly diminished ability to recognize and cleave a Stormorken syndrome-causing mutant Orai1 (P245L)." (PMID 34800360, 2021). "Several dominant GoF mutations in Orai1 and STIM1 have been identified in patients with tubular aggregate myopathy (TAM) and Stormorken syndrome (STRMK)." (PMID 40459545, 2025). "Gain-of-function (GOF) mutations in ORAI1 and STIM1 that result in constitutively active CRAC channels, in contrast, are associated with tubular aggregate myopathy (TAM) or Stormorken syndrome." (PMID 41200103, 2025). "In contrast, gain‐of‐function Orai1 mutations cause tubular aggregate myopathy (TAM), York platelet syndrome, and Stormorken syndrome." (PMID 35581745, 2022). "On the opposite, some gain-of-function mutations in Orai1 or STIM1, allowing a constitutive SOCE or an increased SOCE amplitude are also associated with diseases like the York platelet syndrome or the Stormorken syndrome." (PMID 33371518, 2020). "Both STIM1 and ORAI1 mutations are linked to three separate, but overlapping, disorders: tubular aggregate myopathy (TAM), Stormorken syndrome and York platelet syndrome." (PMID 31666234, 2019). "Furthermore, gain-of-function mutations of Orai1 and STIM1 gave rise to tubular aggregate myopathy (TAM) and Stormorken syndrome (STRMK), forming a clinical spectrum encompassing muscle weakness, myalgia, and cramps, and additional multi-systemic signs, including short stature." (PMID 34638799, 2021).
glioblastoma (17 papers, 2014 to 2023). The most malignant astrocytic tumor (WHO grade IV). "In glioblastoma cells, Orai1 expression is upregulated and linked to their enhanced invasion by controlling the phosphorylation of kinase Pyk2." (PMID 36612099, 2022). "Higher levels of Stim1 and Orai1 mRNA have been detected in human glioblastoma, where they are associated to the higher amplitude of thapsigargin-induced SOCE." (PMID 24603752, 2014). "Found up-regulated in glioblastoma multiforme (GBM), STIM1 and Orai1 are positively associated with GBM invasiveness." (PMID 32599788, 2020). "STIM1 and Orai1 play a significant role in human glioblastoma or glioblastoma multiforme (GBM) cells, a form of aggressive brain malignant tumor which originates from glial cells and astrocytes." (PMID 33333945, 2020). "STIM1 and ORAI1 have been shown to be involved in Ca2+ signaling in both astroglia and glioblastoma cells." (PMID 33424550, 2020). "Our findings show that Synta66 is a highly selective ligand to the Orai1 pore and efficiently blocks store operated calcium entry in glioblastoma cells." (PMID 33036292, 2020). "In another study, pharmacological inhibition of SOCE and ORAI1 silencing, led to decrease in cell proliferation and induction of apoptosis in glioblastoma cells." (PMID 30691160, 2019). "The pharmacological blockade of SOCE did not affect proliferation also in primary cultures of metastatic RCC cells and of glioblastoma cells, although Stim1 and Orai1 promoted migration and invasion in the latter." (PMID 30123430, 2018). "Another research group found that downregulation of STIM1 and Orai1 in primary human glioblastoma cell lines results in a significant decrease in tumor cell invasion in vitro." (PMID 25433371, 2014). "Interestingly, another report revealed that both STIM1 and Orai1 are essential for the survival and proliferation of glioblastoma cell lines." (PMID 33333945, 2020). "Similarly, knockdown of STIM1 or Orai1 in rat and human glioblastoma cells inhibited tumor cell proliferation and promoted apoptosis." (PMID 29783744, 2018). "Moreover, the larger magnitude of agonist-induced SOCE in the human glioblastoma cell line U251 was not accompanied by the up-regulation of the mRNAs encoding for Stim1 and Orai1." (PMID 30123430, 2018). "Synta66, which selectively inhibits Orai1, prevents SOCE in three glioblastoma cell lines (U-87 MG, LN-18, A172)." (PMID 36612099, 2022). "In glioblastoma multiforme, STIM1 and Orai1 knockdown decreased cancer cell invasion and proliferation, respectively." (PMID 32599788, 2020). "The silencing of STIM1 or Orai1 was shown to reduce SOCE and CRAC currents in human glioblastoma cells." (PMID 33424550, 2020). "Electrophysiological recordings in glioblastoma cells and in astrocytes demonstrated that STIM1 and Orai1-mediated SOCE results in highly inward rectifying Ca2+ currents." (PMID 33036292, 2020). "While small interfering RNA (siRNA)-mediated silencing of ORAI1 (but not STIM1) marginally reduces cell proliferation, silencing of both ORAI1 and STIM1 dramatically reduces invasion of glioblastoma cells." (PMID 30691160, 2019). "In brain tumor glioblastoma multiforme (GBM) cells, Orai1 levels were found to be higher than in human primary astrocytes, with an associated increase in the magnitude of SOCE in these cells." (PMID 27417567, 2016). "The complex regulation of the Ca2+ machinery under pathological conditions is further corroborated by the finding that the higher amplitude of SOCE in the human glioblastoma cell line U251 is not mirrored by the up-regulation of Orai1 and Stim1 transcripts." (PMID 24603752, 2014). "Both ORAI1 and STIM-1 are upregulated in primary human cell lines obtained from surgical samples of glioblastoma multiforme compared to non-tumor human astrocytes." (PMID 33122991, 2020). "In primary human glioblastoma cells, higher levels of SOCE and ORAI1 expression have been observed in comparison to non-malignant human primary astrocytes." (PMID 30691160, 2019).
hepatocellular carcinoma (16 papers, 2013 to 2023). A malignant tumor that arises from hepatocytes. "This classical model of STIM1 and Orai1 has been extensively implicated in tumorigenesis of many cancers, including hepatoma, breast, colorectal, prostate, etc., Orai proteins and STIM proteins represent attractive therapeutic targets." (PMID 35269437, 2022). "In hepatoma cells, ORAI1 and STIM2 adapter protein were the predominant forms, while in HepaRG cells, transcription of ORAI3 and STIM1 was much higher, as revealed in RNAseq dataset and by real-time PCR." (PMID 37189460, 2023). "ORAI1 expression was upregulated in several cancer models, including esophageal, squamous, ovarian, and hepatocellular carcinoma cell lines." (PMID 36142596, 2022). "A recent study in human hepatoma cells showed that 5-fluorouracil induced autophagy by decreasing Orai1-dependent SOCE activation." (PMID 31252656, 2019). "A recent study showed that Orai1 and Orai3 stimulated cell growth in Human Embryonic Kidney 293 cells, human hepatoma cells (Huh-7) and HeLa cells independently on their ion-conducting properties." (PMID 30123430, 2018). "Furthermore, Orai1 expression is also elevated in hepatocellular carcinoma (HCC) tissues, and contributes to a chemoresistant phenotype." (PMID 30884858, 2019). "Therefore, this study investigated the functional consequences of enhanced expression of STIM1 and Orai1 in a tumor-initiating subpopulation of Huh-7 hepatocellular carcinoma (HCC) cells that express epithelial cell adhesion molecule (EpCAM) and Prominin 1 (CD133)." (PMID 31366337, 2019). "The link between ORAI1 and the PI3K/AKT pathway in chemotherapeutic agent resistance has also been reported in a hepatocellular carcinoma cell line (HepG2) exposed to 5-FU." (PMID 36142596, 2022). "In this study, we systematically evaluated the genetic susceptibility between the store-operated calcium (SOC) influx pathway (stromal interaction molecule 1 (STIM1) and ORAI1) and human hepatocellular carcinoma (HCC) in patients with chronic hepatitis B (CHB) infection." (PMID 33182378, 2020). "First, they are differentially expressed in malignant cells and STIM1 and ORAI1 were found to be more strongly expressed in hepatoma tissues than in pre-cancerous tissues or non-tumoral tissues from the same patients." (PMID 30338034, 2018). "Moreover, in human hepatoma cell line Huh-7, it has been also shown that Ca2+ entry involving TRPC6, together with STIM1 and Orai1, increases cyclin D1 expression." (PMID 24058448, 2013). "The purpose of this study is to investigate possible HBV origins of specific microRNAs we identified in a stem cell-like subpopulation of Huh-7 hepatocellular carcinoma (HCC) cell lines with enhanced STIM1 and/or Orai1 expression that mimicked poor cancer prognosis." (PMID 36556285, 2022).
triple-negative breast carcinoma (15 papers, 2018 to 2025). An invasive breast carcinoma which is negative for expression of estrogen receptor (ER), progesterone receptor (PR), and human epidermal growth factor receptor 2 (HER2). "For instance, Orai1 expression is enhanced in the estrogen receptor-positive (ER+) and triple-negative subtypes, and both triple-negative breast cancer (TNBC) differentiated cells and stem cells are remarkably dependent on Orai1 expression and function." (PMID 39061158, 2024). "Here, we show that Orai1 plays an essential role for agonist-induced Ca2+ entry in triple negative breast cancer-derived BCSC, which is required for spheroid-forming efficiency and COX activity in these cells." (PMID 37945647, 2023). "Orai1 is upregulated in estrogen receptor positive (ER+) and triple negative breast cancer cells and this channel regulates the transcription of genes that contribute to cancer progression." (PMID 36612199, 2022). "Orai1 plays a major role in store-operated Ca2+ entry (SOCE) in triple-negative breast cancer (TNBC) cells." (PMID 31652779, 2019). "Similarly, SOCE in triple negative breast cancer cells is strongly dependent on Orai1 and, subsequently, the development of a variety of cancer hallmarks, such as cell proliferation, migration or apoptosis resistance." (PMID 37945647, 2023). "Leflunomide and Teriflunomide inhibit SOCE in triple-negative breast cancer cells overexpressing Orai1, but not in cells overexpressing Orai3." (PMID 38541682, 2024). "Here we show that while STIM1 and Orai1 N-linked glycosylation has a significant effect on SOCE in non-tumoral breast epithelial cells, both ER+ and triple negative breast cancer (TNBC) cells are unaffected by this mechanism." (PMID 36612199, 2022). "In the present study we have investigated the role of STIM1 and Orai1 N-linked glycosylation in SOCE in non-tumoral breast epithelial cells as well as in ER+ and triple negative breast cancer (TNBC) cells." (PMID 36612199, 2022).
breast tumor (14 papers, 2009 to 2025). "This is sustained by the observation that the oncogenic activity of breast tumor cells is increased by the activation of ion channel Orai1 through a molecular interaction with the Ca2+ pump secretory pathway Ca2+ ATPase." (PMID 39716493, 2024). "Proliferation of breast tumor cells strongly depends on the Ca2+-homeostasis, as evidenced by the fact that silencing of Orai1, the main component of the store operated Ca2+ entry (SOCE), decreased the proliferation of the MDA-MB-231 cells." (PMID 31973006, 2020). "SKF96365, a drug that blocks several Ca2+ permeable channels including TRPM7 and CRAC/Orai1, reduced migration of a breast tumor cell line." (PMID 23620825, 2013). "Thus androgens upregulated the Ca2+ influx channel Orai1 in MCF-7 breast tumor cells, while in LNCaP cells, androgens were shown to increase cytosolic Ca2+ by enhancing Ca2+ influx through L-type channels, and via G-protein-coupled receptors." (PMID 34199520, 2021). "By contrast, in breast tumor cells, ORAI1 knockdown inhibited focal adhesion turnover." (PMID 34831241, 2021). "Indeed, Kv10.1 was observed expressed alongside Orai1 in invasive breast tumors and lymph node metastasis, and regulates cell migration through an Orai1-dependent constitutive Ca2+ entry." (PMID 34209733, 2021). "A reduction in ORAI1 or STIM1, both of which are essential for store-operated calcium entry, in breast tumour cells decreased tumour metastasis." (PMID 27347718, 2016). "The present study explored, whether mAR activation is followed by alterations of Orai1 protein abundance and function in MCF-7 breast tumor cells and addressed the role of actin reorganization and actin signaling to this effect." (PMID 26690689, 2015). "Whether this involves store-operated Ca2+ entry requires further investigation; however, it also is noteworthy that Orai1 and STIM1 are critical for breast tumor cell migration and metastasis." (PMID 19778436, 2009).
cardiac hypertrophy (14 papers, 2017 to 2024). "Adult mice subjected to transverse aortic constriction (TAC) developed cardiac hypertrophy and reduced ventricular function associated with increased Orai1 expression and Orai1-dependent SOCE (assessed by Mn2+ influx)." (PMID 31906693, 2020). "Several studies proposed a pathological key role for STIM1/Orai1-mediated SOCE in altered Ca2+ signaling underlying the development of cardiac hypertrophy by changing the fetal gene program regulated by NFAT signaling." (PMID 29618985, 2018). "Our results suggest that targeting Orai1–Drp1 axis may offer a promising approach to ameliorate the cardiac hypertrophy associated with type 2 DM." (PMID 33637715, 2021). "Notably, the majority of published data suggest that excessive Ca2+ influx through Orai1/SOCE is a causative factor for pathological cardiac hypertrophy." (PMID 34079454, 2021). "It is moderately potent and highly selective for ORAI1 over other Ca2+-permeable channels and was well-tolerated and effective in a mouse model of cardiac hypertrophy and rat model of pulmonary hypertension." (PMID 38261554, 2024). "Specifically, inhibition of Orai1 was shown to reduce cardiac hypertrophy and improve mitochondrial function through reductions in Drp-1, calcineurin, and ERK1/2 activities." (PMID 35821821, 2022). "Since the establishment of a role for STIM1/Orai1 in cardiac hypertrophy, several additional studies have tried to examine the mechanisms driving the increase in STIM1 during hypertrophy." (PMID 35821821, 2022). "Together, these data suggest that Ang II promotes excessive cardiomyocyte autophagy through SOCE/Orai1 which can be the prime contributing factors in cardiac hypertrophy." (PMID 34079454, 2021). "Here, we found that SOCE and Orai1 situate upstream of autophagic signaling cascade to trigger cardiac hypertrophy, involving Orai1-Ca2+-autophagy-hypertrophy." (PMID 34079454, 2021). "We next examined the role of Orai1 by employing the mouse model of Ang II-induced cardiac hypertrophy." (PMID 34079454, 2021). "The present review will survey our current knowledge on the expression and function of Orai1 in the heart and on its participation to cardiac hypertrophy and HF." (PMID 33117812, 2020). "Even if its cardiac physiological role in adult is still elusive and needs to be clarified, Orai1 contribution in cardiac diseases such as cardiac hypertrophy and heart failure (HF) is increasingly recognized." (PMID 33117812, 2020). "In pressure overload-induced cardiac adaptive hypertrophy in mice, overexpression of SARAF in the heart prevented Orai1 upregulation and attenuated the cardiac hypertrophy." (PMID 33117812, 2020). "SOCE has recently emerged as a key contributor of cardiac hypertrophy and heart failure but the relevance of Orai1 is still unclear." (PMID 31906693, 2020). "Taken together, these data indicate that gastrodin acts to suppress the expression of STIM1 and Orai1 proteins in both in vivo and in vitro models of cardiac hypertrophy." (PMID 28487655, 2017). "However, upon the discovery of STIM1 and Orai1 as key regulators of SOCE and with STIM1/Orai1-mediated SOCE being associated with cardiac hypertrophy, there was a growing appreciation of this signaling mechanism in the heart." (PMID 35821821, 2022). "We hypothesized that Orai1-mediated SOCE promotes cardiac hypertrophy induced by high glucose (HG) via regulation of Drp1 phosphorylation." (PMID 33637715, 2021). "Consistent with previous results, Orai1 knockdown may play a role in myocardial hypertrophy by reducing CnA and ERK1/2 activity." (PMID 33637715, 2021). "Our findings support the idea that Orai1 inhibition can improve Ca2+ cycling and systolic cardiac function during hypertrophic stress, suggesting that selective Orai1 blockade might provide a new therapy for cardiac hypertrophy and HF." (PMID 31906693, 2020).